TSC1 (TSC complex subunit 1)
Diseases named in the same sentence as TSC1 in open-access papers (continued):
Sharing a sentence is not in itself a finding about the gene and the disease.
autism (continued). "Since mounting evidence has established autism as a disorder of the synapses, we tested whether rare genetic variants in TSC1, TSC2, MYCBP2, RHEB and FBXO45, genes that regulate mTORC1 signaling and/or play a role in synapse development and function, contribute to the pathogenesis of idiopathic ASD." (PMID 23514105, 2013). "Purkinje cell–specific deletion of the Tsc1 gene has been shown to lead to autism-like deficits and has been used to test pharmacological interventions." (PMID 39262819, 2024). "To perturb the developing cerebellum in a manner that more closely models human diseases, we used the Pcp2Cre/+ mouse to delete the tuberous sclerosis (TSC) complex subunit 1 (Tsc1) gene in Purkinje cells, which is an established mouse model for autism." (PMID 39558452, 2024). "Between 30% and 60% of people who harbor loss-of-function mutations in the TSC1 and TSC2 genes receive an autism diagnosis, with mutations in the TSC2 gene showing a higher risk." (PMID 39262819, 2024). "This study elucidated molecular, cellular, and electrophysiological changes in the mammalian brain caused by reduced dosage of Tsc1, which underlies TSC with comorbid seizures and autism." (PMID 38201256, 2023). "In experimental studies, conditional deletion of the Tsc1 gene in Purkinje cells leads to mTORC1 hyperactivation and autism-like behaviors in mice." (PMID 35682995, 2022). "Mutations in the TSC1/TSC2 genes lead to the overactivation of mTOR signalling, which is also linked to nonsyndromic autism." (PMID 34576223, 2021). "Further, our cell-based data is consistent with the recent addition of PPP2R5D to the list of autism susceptibility genes related to AKT3, PIK3CA, PTEN, TSC1/2, and mTOR." (PMID 33482199, 2021). "The most direct evidence comes from monogenic, syndromic forms of autism, many of which are caused by lost or reduced function in genes, including eIF4E, FMR1, PTEN, NF1, TSC1, TSC2 and PRKCB1, that negatively regulate the pathway or its subsystems." (PMID 31548888, 2019). "An ASD study that identified rare variants in mGLUR signaling pathway reported rare and deleterious variants in the SHANK3, TSC1, and TSC2 genes in non-syndromic autism individuals." (PMID 31744938, 2019). "Gene defects associated with upstream regulators of mTOR (TSC1, TSC2, and PTEN), are associated with autism and in many cases, macrocephaly." (PMID 31024350, 2019). "Pharmacological treatments based on inhibition of this pathway have been developed and tested in mouse models for Fragile X syndrome, eIF4E dysregulation, and TSC1 and TSC2, with amelioration of autism-associated deficits in all cases." (PMID 31548888, 2019). "For example, an abnormal USV developmental profile with an elevated call rate at P9-10 has been seen in the Ts65Dn mouse model of Down’s syndrome and the Purkinje cell Tsc1 KO mouse model of autism." (PMID 29920554, 2018). "Translation has been an important topic in ASD primarily because of work on syndromic forms of autism related to mutations in FMR1, TSC1/2, and PTEN, as well as the important cap-dependent translation gene EIF4E." (PMID 28649314, 2017). "Several genes that often occur in minority polymorphisms in autism (FMR1, Tuberous Sclerosis complex 1 and 2 -TSC1, TSC2, and phosphatase and tensin homolog-PTEN) and the STEP protein that is upregulated in FXS65 are associated with these pathways." (PMID 27212113, 2016). "Although some of the genes studied are known to cause syndromic ASD (e.g. FMR1, TSC1, TSC2, UBE3A), their possible role in non-syndromic autism has been unclear." (PMID 22558107, 2012).
autism (continued). "At the level of individual pathway genes, we identified a significant excess of SNVs in the autism population for the TSC1, TSC2, SHANK3, and HOMER1 genes (P<0.05)." (PMID 22558107, 2012). "The over-representation of rare, potentially disruptive variants in genes previously implicated in ASD (TSC1, TSC2, SHANK3) provides validation of this approach to detect genes that contribute genetic risk in autism." (PMID 22558107, 2012). "Although some ASD mouse models exhibit a reduced E/I ratio, such as mice with autism-associated mutations in NRXNs or SHANKs, an enhanced E/I ratio can also be observed in many other ASD mouse models, such as TSC1-, MDGA2-, FMRP-, or CUL3-deficient mice." (PMID 34848499, 2022). "Atypical Purkinje cell structure and function have been reported in the tuberous sclerosis mouse model of autism (TSC1;), and chemogenetic stimulation of Purkinje cells rescued social impairments in TSC1 mice, critically linking cerebellar dysfunction to core autism behaviors." (PMID 32632709, 2020). "Loss of function in multiple genes that negatively regulate mTOR, including TSC1, TSC2, PTEN, NF1, and FMR1, has been linked to syndromic autism with increased head size and high rates of seizures; both of these traits are also found in mice heterozygous for AMBRA1 loss of function." (PMID 31687209, 2019). "This discrepancy likely reflects that the ARRA Autism Sequencing Collaboration cohort we used contains few syndromic cases (e.g., autistic patients with syndromic mutations in tumor suppressor genes, such as NF1, PTEN, TSC1/2)." (PMID 26934580, 2016). "Pten gene is considered as susceptible for autism as Fragile X protein (FXS) and Tuberous sclerosis protein complex 1 and 2 (TSC1/2 complex), and PTEN mutations may account as much as 5% of autism associated with macrocephaly and 1% of autism." (PMID 27071011, 2016). "Mutations in the TSC genes, TSC1 and TSC2 are known to cause syndromic autism." (PMID 23514105, 2013). "Finally, selective genetic knockout (KO) of the Tsc1 gene in mouse cerebellar Purkinje cells reproduces several autism behavioral phenotypes." (PMID 24151553, 2013). "Causal roles for TSC1 and TSC2 have previously been demonstrated in syndromic autism." (PMID 22558107, 2012). "Although significant enrichment of rare, potentially disruptive variants in AGRE samples relative to controls was limited to the TSC1, TSC2, SHANK3, and HOMER1 genes, individual variants in additional genes suggest a role for the Ras/ERK cascade in autism susceptibility." (PMID 22558107, 2012). "Interestingly, our analysis revealed a significant excess of rare, potentially deleterious variants in three known autism genes, SHANK3, TSC1, and TSC2, in individuals with non-syndromic autism." (PMID 22558107, 2012). "Moreover, it was shown that inhibition of mTOR improves ASD-like behaviours related to Tsc2 or Tsc1 haploinsufficiency (in several Tsc1+/− or Tsc2+/− animal models), pointing to mTOR attenuation as an effective strategy in various mTOR-related brain dysfunctions, including autism." (PMID 37108467, 2023). "Furthermore, the authors demonstrated that chemogenetic manipulation of components of this circuit could improve autism-related behaviours observed in the Purkinje cell specific Tsc1 mouse model." (PMID 38075533, 2023). "In most patients, TSC1/2 mutations impact central nervous system function, resulting in infantile seizures, intractable epilepsy, and TS-associated neuropsychiatric disorders (TAND), including autism, attention deficits, intellectual disability, and mood disorders." (PMID 36506334, 2022).
autism (continued). "Studies from different animal models, including Tsc1, Shank 2, and PTEN KO mice, suggest that attenuated firing of PNs is a recurring denominator for autism." (PMID 30224722, 2020). "Inhibition of this increased activity has been shown to improve autism-related symptoms in mouse models of PTEN and TSC1." (PMID 31827489, 2019). "Finally, as we identified four proteins (p-eIF4E, rpS6, TSC1 and p-MNK1) that demonstrated an association with the clinical severity, we wanted to investigate if, together, those proteins could constitute a molecular signature for autism severity." (PMID 30705255, 2019). "Other candidate genes of autism include NF1, PTEN, MET, TSC1, TSC2, and CYFIP1, that are located in the duplication region (15q11–13)." (PMID 31744938, 2019). "Two recent studies looked at the possible role of TSC1 and TSC2 genes along with others in non-syndromic autism." (PMID 23514105, 2013). "A recent study also identified a number of SNVs in the TSC1, TSC2, and SHANK3 genes in simplex autism cases (although the frequency of SNVs in these genes in controls was not reported)." (PMID 22558107, 2012). "Molecular changes may also influence the expression of genes involved in autism symptoms and genetic syndromes such as GABRB3, FMR1, TSC1 and TSC2." (PMID 29340132, 2018). "Although the manifestations of TSC include ASD in up to 50% of cases, our findings additionally implicate TSC1 and TSC2 as risk genes for non-syndromic autism independent of their causative role in TSC." (PMID 22558107, 2012). "Our findings recall the observation that men are identified as being on the autism spectrum four times as often as women, and would be consistent with the possibility that regulation of some genes (by our measures, Cntnap2) but not others (Tsc1) might have differential effects by sex." (PMID 35279205, 2022).
hamartoma (47 papers, 2008 to 2025). A benign and excessive tumor-like growth of mature cells and normal tissues which grow in a disorganized pattern. "Tuberous sclerosis complex (TSC) is an autosomal dominant genetic disease characterized by the presence of hamartomas affecting multiple systems in the body, caused by loss-of-function mutations in the TSC1 or TSC2 genes." (PMID 39119187, 2024). "In a study of 111 TSC-associated tissues, two-thirds of hamartomas were found to contain two hits to TSC1/TSC2, including most SEGAs, SENs, and renal angiomyolipomas, as well as 35% of tubers." (PMID 38540392, 2024). "A loss of function of Tsc1/2 causes mTORC1 activation and an increase in syntenin through Rheb1 activation, promoting the cell proliferation observed in hamartoma cells with TSC pathology." (PMID 36606143, 2022). "Subtle differences between loss of Tsc1 and Tcs2 have been seen in many other studies, including in humans with hamartomas, which are benign tumors that are caused by loss of either gene." (PMID 34208233, 2021). "We analyzed the immune competence by characterizing PBMC of two TSC Italian families, carrying distinct monoallelic TSC1 germline mutations identified in hamartomas in various anatomical locations." (PMID 24633152, 2014). "Since hamartomas are frequently observed in brain, kidney and skin, but have not been associated with hematological malignancies, we investigated the effect of TSC1 down-regulation in transformed Jurkat cells." (PMID 24633152, 2014). "Tuberous sclerosis complex (TSC) is a human genetic disorder in which loss of either TSC1 or TSC2 leads to development of hamartoma lesions, which can progress and be life-threatening or fatal." (PMID 22363765, 2012). "Loss of TSC1/TSC2 in TSC hamartomas leads to both activation of mTORC1, as well as feedback inhibition of AKT, through downregulation of IRS and PDGFR expression and other mechanisms." (PMID 19527517, 2009). "For many years, the prevailing model has been that the hamartomas of TSC develop through a two-hit mechanism in which there is complete loss of expression of functional TSC1 or TSC2, supported by findings of loss of heterozygosity (LOH) in TSC tumour samples." (PMID 19506736, 2008). "In support of this notion, hamartomas associated with mutations in TSC1 or TSC2 (tuberous sclerosis complex 1 and 2) genes in humans have been phenocopied in zebrafish by the generation of mosaic embryos that carry wild-type and tsc2 (vu242/vu242) mutant cells." (PMID 29716894, 2018). "However, efforts to model hamartomas have largely been unsuccessful, in part due to the early lethality of homozygous germline mutations in Pten and other hamartoma-associated genes, such as tuberous sclerosis genes (Tsc1/Tsc2)." (PMID 29716894, 2018). "Loss of Tsc1/Tsc2 results in excess cell growth that eventually forms hamartoma in multiple organs." (PMID 26795955, 2016). "Loss of either TSC1 or TSC2 in TSC hamartomas leads to activation of mTORC1 and suppression of AKT." (PMID 19527517, 2009). "TSC is an autosomal dominant neurocutaneous disorder caused by mutations in TSC1 or TSC2, clinically characterized by the development of hamartomas across multiple organ systems." (PMID 41142004, 2025). "The activation of the mTOR pathway due to genetic alterations of the tuberous sclerosis complex in the TSC1 or TSC2 genes in hamartomas has also been reported as well as the subsequent therapeutic implications." (PMID 38622693, 2024). "Tuberous sclerosis complex (TSC) is a multisystem monogenetic disorder caused by mutations in either TSC1 or TSC2 and is characterized by hamartoma development in several organs, including the brain, kidneys, lungs, heart, eyes, and skin." (PMID 34709498, 2022). "It is caused by a mutation in either the TSC1 or TSC2 gene and is characterized by the development of tumours or hamartomas in many organs." (PMID 36362447, 2022).
hamartoma (continued). "The pathogenesis of TSC is that heterozygous mutations in the either TSC1 gene or TSC2 gene lead to overaction of mTOR signaling pathway, resulting in excessive cell growth and the formation of hamartomas in multiple systems throughout the body." (PMID 35467404, 2022). "TSC1 and TSC2 variants are thought to result in a loss of function, leading to multiple organ hamartias and hamartomas." (PMID 32211034, 2020). "Individuals with TSC are heterozygous for loss-of-function germline mutations in either of the tumor-suppressor genes TSC1 or TSC2, and they can have benign tumors called hamartomas in multiple organs such as the brain, heart, skin, lungs, and kidney." (PMID 32075691, 2020). "The similar behaviors of PTEN and Tsc1 FoxO mutant tissues suggest that the loss of FoxO contributes to the transformation of benign growth of Tsc1 mutant hamartomas into malignant tumors." (PMID 29677182, 2018). "Tuberous sclerosis complex (TSC) is a rare genetic disorder caused by a mutation of TSC1 or TSC2 and characterized by the multisystemic growth of tumor‐like lesions called hamartomas." (PMID 29881807, 2018). "For example, TSC is caused by a mutation of TSC1 or TSC2 that disrupt the mTOR pathway and is characterized by multisystem growths of tumor-like lesions called hamartomas, which can affect a wide-range of bodily systems." (PMID 30733689, 2018). "Loss-of-function mutations to Tuberous Sclerosis Complex 1 (TSC1) and TSC2 are responsible for the hamartoma condition, TSC." (PMID 29301334, 2018). "We discovered that roughly two-thirds of hamartomas from TSC1/TSC2 patients harboured two TSC hits, including most RAs and SEN/SEGAs, while second hits were found in only 35% of cortical tubers." (PMID 28643795, 2017). "It occurs due to inactivating mutations in either of the two genes, TSC1 and TSC2, following a second hit in a tumor suppressor gene in most hamartomas." (PMID 28968464, 2017). "It is thought that tuber/hamartoma development requires “two hits,” whereby a germline mutation in one allele of TSC1 or TSC2 is complemented by a second somatic mutation in the other allele, leading to cell growth derangement and hamartoma formation." (PMID 28367137, 2017). "TSC occurs due to inactivating mutations in either of two genes, TSC1 in chromosome 9q34 or TSC2 in chromosome 16p13, and follows the two hit tumor suppressor model of pathogenesis in most hamartomas." (PMID 28968464, 2017). "Mutations in the tumor suppressor genes encoding TSC1 (Hamartin) and TSC2 (Tuberin) lead to a multisystemic tumor syndrome called tuberous sclerosis, which is characterized by neoplastic lesions (i.e., hamartomas)." (PMID 26877878, 2016). "Tuberous sclerosis complex (TSC), a tumor syndrome caused by mutations in TSC1 or TSC2 genes, is characterized by the development of hamartomas." (PMID 18958173, 2008). "Mutations in the TSC1 and TSC2 genes result in the constitutive hyperactivation of the mammalian target of the rapamycin (mTOR) pathway, contributing to the growth of benign tumors or hamartomas in various organs." (PMID 39852149, 2025). "Furthermore, loss of heterozygosity (LOH) of TSC1 or TSC2 has been reported in approximately 80% of SEGAs and has also been found in other TSC hamartomas." (PMID 34709498, 2022). "TSC1/TSC2 mutations will cause dysfunction of the complex, resulting in activation of the mTOR signaling pathway, thus inducing the occurrence of TSC-related benign tumors or hamartomas in multiple systems." (PMID 34217357, 2021). "The nutrient fluctuations in the microenvironment of hamartomas may also enhance tumor progression, as is seen by the dramatic overgrowth of the Tsc1 FoxO mutant tissue upon NR." (PMID 29677182, 2018). "Interestingly, these negative regulators of mTOR, that is, TSC1, TSC2, and LKB1, are tumor suppressors, and germline mutations of TSC1/2 or LKB1 cause hamartomas and predisposition to multiple malignancies in humans." (PMID 22666248, 2012).
hamartoma (continued). "Mutations on either of the two genes Tuberous Sclerosis Complex 1 (TSC1) or Tuberous Sclerosis Complex 2 (TSC2) play a role and result in hamartomas involving many organs, like the brain, heart, kidneys, skin, lungs, and liver." (PMID 33552794, 2021). "Disruption in the TSC1/TSC2 complex leads to constitutive activation of mTORC1, resulting in unchecked protein synthesis, cell cycle progression, and ultimately the development of benign tumors, or hamartomas, characteristic of TSC." (PMID 40722560, 2025). "This has led to speculation that treatment of TSC hamartomas with mTORC1 inhibitors might lead to restoration of AKT activation, as seen in vitro with treatment of TSC1/TSC2 null cells, and in some patients with malignant disease, which may compromise clinical benefit." (PMID 19527517, 2009). "mTORC1 is constitutively activated in cells lacking either TSC1 or TSC2 and in hamartomas from TSC patients." (PMID 22363765, 2012).